INS (insulin)
Diseases named in the same sentence as INS in open-access papers (continued):
Sharing a sentence is not in itself a finding about the gene and the disease.
Insulin resistance (continued). "We highlighted Candida and certain types of bacteria since previous in vitro research showed they significantly affect insulin secretion and can cause insulin resistance in obese patients with metabolic syndrome." (PMID 36397429, 2022). "Peripherally, asprosin directly affects insulin signaling causing increased insulin resistance, inflammation, and endoplasmic reticulum stress." (PMID 36686442, 2022). "Delineating the cause–effect relationship between reduced insulin clearance and insulin resistance has been complicated by the fact that insulin action and clearance are mechanistically linked to insulin binding to its receptors." (PMID 36009446, 2022). "Several small TRE studies have reported reductions in insulin resistance, and by inference insulin levels, that would be expected to reduce cancer risk." (PMID 35984550, 2022). "Several inflammatory signaling pathways are implicated in inhibiting insulin functions, which can link inflammation to insulin resistance." (PMID 36230963, 2022). "Insulin resistance in hepatocytes causes impaired insulin signaling and decreased glucose uptake, the major contributors of hyperglycemia." (PMID 35571083, 2022). "Low doses of Dexa were found to decrease insulin sensitivity, resulting in hyperinsulinemia and impaired glucose tolerance, increasing the risk of insulin resistance and subsequently developing type 2 diabetes." (PMID 35883763, 2022). "The increased storage of lipids in insulin-sensitive tissues (such as skeletal muscle) was shown to be the main cause of decreased aerobic capacity, insulin resistance, and impaired glycogen synthesis." (PMID 36145123, 2022). "It was previously established that dysregulation of BCAA metabolism is a hallmark of obesity and insulin resistance, with obese/insulin-resistant individuals being characterized by elevated levels of serum BCAA." (PMID 35264213, 2022). "Because insulin regulates this pathway, insulin resistance causes an increase in the free fatty acid release from adipose tissue and poor removal of triglyceride‐rich lipoproteins." (PMID 35734805, 2022). "Hyperglycemia due to insulin resistance causes increased secretion of insulin, which increases energy requirements and upregulates gluconeogenesis in the liver." (PMID 35565920, 2022). "Insulin resistance, is caused by lipid metabolic abnormalities and elevated levels of circulating fatty acids that accumulate in insulin-sensitive organs such muscle, liver,and adipose tissues." (PMID 35815199, 2022). "The activation of IRS-1/Akt signal pathway caused enhanced insulin action and then improved insulin resistance in rats fed with a high fat diet as shown in our study." (PMID 35487948, 2022). "Impairment in insulin-stimulated GLUT4 exocytosis is a hallmark of insulin resistance and type 2 diabetes." (PMID 36087838, 2022). "Reducing insulin concentrations via weight reduction and thereby a reduction in insulin resistance, thus positively influences cardiovascular risk factors." (PMID 35817987, 2022). "Another strong regulator of plasma glucagon is insulin, and insulin resistance and type-2-diabetes are strongly associated with both fasting and postprandial hyperglucagonemia." (PMID 36088386, 2022). "Glucocorticoids used after transplantation cause dose-dependent peripheral and central insulin resistance and suppress insulin-related lipolysis." (PMID 36402951, 2022). "Obesity stimulates NF-κB, JNK, and other signaling pathways to promote the expression of inflammatory factors, thus influencing the insulin signaling pathway and causing insulin resistance." (PMID 35757707, 2022). "Increased oxidative stress has also been implicated in insulin resistance and β‐cell injury resulting in a decline in insulin secretion." (PMID 35432973, 2022).
Insulin resistance (continued). "As with other ectopic fat depots, ectopic muscle fat has the potential of impairing insulin action through the inhibition of insulin signaling by lipotoxic diacylglycerols and ceramide and cause insulin resistance." (PMID 35432188, 2022). "Animal studies have shown that vitamin D is important for insulin synthesis and can improve the body’s sensitivity to insulin, reducing the risk of insulin resistance." (PMID 35457041, 2022). "Further, heart failure is associated with insulin resistance and increased sympathetic nerve activity, the latter known to inhibit insulin secretion and stimulate both hepatic gluconeogenesis and glycogenolysis." (PMID 35733766, 2022). "Sleep variability was also associated with increased daily insulin requirement, suggesting more insulin resistance in these individuals." (PMID 35986415, 2022). "Reduction of insulin also would be expected to contribute to cognitive benefit given the strong association of insulin resistance and associated hyperinsulinemia with neurocognitive decline and progression of neuropathology." (PMID 35458181, 2022). "Via autocrine and paracrine effects of proinflammatory molecules, inflammation can interfere with whole-body insulin signaling or induce β-cell dysfunction and subsequent insulin deficiency, resulting in obesity-related insulin resistance." (PMID 36505236, 2022). "The inability to respond to insulin to clear blood glucose (insulin resistance) is a key pathogenic driver of the disease." (PMID 35277006, 2022). "A surplus number of metabolites of TG and FFA can restrict the stimulation of phosphatidylinositol-3-kinase (PI3K)/Akt, thus causing a dip in the downstream signaling actions of insulin and resulting in insulin resistance." (PMID 36290804, 2022). "As a result, increased fasting insulin concentrations precede the development of hyperglycemia caused by insulin resistance, with this elevation in fasting insulin occurring at normoglycemic values." (PMID 34823065, 2022). "The definition of insulin resistance at peripheral tissues would seem easy to identify: whenever more than “normal” levels of insulin are needed to maintain blood glucose levels, insulin resistance is the presumptive cause." (PMID 35884888, 2022). "Excessive gestational weight gain leads to increased insulin resistance and islet β-cell depletion, so that β-cells cannot secrete enough insulin to compensate for insulin resistance caused by pregnancy, leading to the occurrence of GDM." (PMID 35872998, 2022). "Dysregulated organelles contribute to systemic inflammation, which causes insulin resistance by inhibiting the insulin signaling pathways." (PMID 36552805, 2022). "The most comprehensive systematic review of genetic susceptibility to GDM (from 23 studies) revealed association with T2D risk variants from seven loci, of which six are related to insulin secretion and one to insulin resistance." (PMID 35220425, 2022). "Meanwhile, a number of studies have found that the abnormal activation of mTORC1 in the central insulin signaling pathway in T2D patients can cause insulin resistance." (PMID 35321336, 2022). "Insulin resistance is caused by a diminished sensitivity of tissue to insulin and corresponds to the failure of the pancreas to generate appropriate amounts of insulin for blood glucose control." (PMID 35711466, 2022). "T2DM is caused by a combination of two primary factors: defective insulin secretion by pancreatic β-cells and chronic insulin resistance in insulin-sensitive tissues." (PMID 36232291, 2022). "Relative hepatic insulin resistance caused by impaired insulin pulsatility and impaired insulin clearance, as well as hyperglucagonemia, both play a crucial role in NAFLD development and are both present in T1D." (PMID 36531463, 2022). "Progressive loss of β-cell insulin action and/or secretion, frequently on the background of insulin resistance." (PMID 39872972, 2022).
Insulin resistance (continued). "On the other hand, reduced insulin clearance in the liver can cause chronic hyperinsulinemia, followed by downregulation of insulin receptor and insulin resistance." (PMID 36009446, 2022). "These metabolic processes can interfere with insulin signalling pathways, contributing to the development of insulin resistance, type 2 diabetes (T2D) and other obesity-associated metabolic diseases." (PMID 36387874, 2022). "DM is mainly induced by two causes: the impairment of insulin secretion (insulin deficiency) and insulin resistance." (PMID 35846289, 2022). "Third, while insulin exerts anti-inflammatory effects, inflammation is also the primary cause of insulin resistance in the brain (Holscher, 2019)." (PMID 36117625, 2022). "In children and adolescents, many but not all authors described positive associations between irisin and insulin or glucose levels, and insulin resistance." (PMID 35774143, 2022). "Impaired insulin responsiveness/insulin resistance is commonly linked to serine phosphorylation of IRS-1; phosphorylation of IRS-1 on Ser307 (human Ser312) results in its dissociation from the insulin receptor, and also impairs insulin downstream signaling." (PMID 35739993, 2022). "Patterns involving prolonged exposure of plasma insulin and a failure to return to basal level have been implicated in the development of insulin resistance and type 2 diabetes." (PMID 35308275, 2022). "An increase in TNF-α was associated with insulin resistance, increased plasma glucose, and insulin prior to the onset of T2DM." (PMID 36140983, 2022). "In human, excessive visceral fat deposition is a major determinant of insulin resistance, but increased subcutaneous fat improves insulin sensitivity and reduces the risk of developing type 2 diabetes." (PMID 35647086, 2022). "We also performed glucose tolerance and insulin sensitivity tests to examine the effect of LXN deficiency on HFD-induced insulin resistance." (PMID 35210404, 2022). "Compared to the first quartile, the fourth DASH quartile was inversely associated with log serum insulin (μIU/mL) [β = −0.19, p = 0.0034] and log-Homeostatic Model Assessment of Insulin Resistance [β = −0.25, p = 0.0008]." (PMID 35215546, 2022). "Insulin resistance is caused by the disruption of insulin signal transduction, which requires the participation of various proteins, such as insulin, insulin receptor, PI3-K, and glucose transporters." (PMID 34976192, 2022). "Lactate in large quantities is synthesized by fat cells in obesity, and its elevated blood levels are associated with insulin resistance and, therefore, its reduction can be seen as further evidence of improved tissue sensitivity to insulin." (PMID 36430664, 2022). "Hyperglycemia is a disease caused by the insufficient secretion of insulin or the insulin’s biological effects being compromised (such as insulin resistance), or a combination of both." (PMID 36558381, 2022). "PTP1B is widely expressed in insulin-sensitive peripheral tissues such as adipose and skeletal muscle tissues, and it can cause both insulin resistance and T2DM." (PMID 36080485, 2022). "The goal of this study was to determine the pattern of leptin gene and receptor polymorphism in insulin resistant and insulin sensitive pregnant women, as well as its relationship to insulin resistance." (PMID 36128550, 2022). "Excessive alcohol consumption can disturb glucose hemostasis by inhibiting insulin secretion and causing whole‐body insulin resistance." (PMID 34738737, 2022). "The aim of this study was to investigate SCT associations with physical activity, markers of insulin secretion (β‐cell function), insulin resistance, and glucose tolerance among PLWH and HIV‐uninfected adults." (PMID 35167170, 2022). "In T2DM, where early disease causes insulin resistance and chronically elevated insulin levels, the neuropathology diverges from T1DM." (PMID 35631433, 2022).
Insulin resistance (continued). "In fact, insulin stimulates apelin synthesis and release in adipocytes, and plasma apelin level markedly increases in obesity associated with insulin resistance and hyperinsulinemia." (PMID 35610700, 2022). "In the first days of life, EPIs frequently develop transient glucose intolerance, which has a complex pathophysiology that associates unregulated gluconeogenesis, immature insulin secretion, and peripheral insulin resistance." (PMID 36144251, 2022). "T2DM is a chronic, low-grade inflammatory disease characterized by hyperglycemia that results from a progressive beta-cell impairment, insulin secretion deficiency, and concomitant insulin resistance." (PMID 36614057, 2022). "Much is known about the molecular mechanisms of insulin resistance in the principal clinical conditions that are associated with decreased insulin sensitivity." (PMID 36289636, 2022). "In both studies, the increase in blood pressure was associated with an increase in insulinemia (insulin levels) and insulin resistance." (PMID 35492316, 2022). "Impairment of autophagy also promotes dysregulation of insulin signaling, leading to impaired glucose clearance and ultimately metabolic syndrome-associated insulin resistance." (PMID 35308126, 2022). "As lipid-induced insulin resistance is a hallmark of fatty liver disease, we additionally analyzed the phosphorylation status of kinases following stimulation with insulin." (PMID 36009822, 2022). "Due to the importance of hypothalamic insulin signaling in the regulation of neuromodulatory and neuroprotective processes, the development of insulin resistance in the hypothalamus is often associated with neurodegenerative events." (PMID 35883638, 2022). "Insulin resistance is induced by the inhibition of insulin-stimulated glucose metabolism, which is caused by increased FFAs from expended adipose tissues." (PMID 36613000, 2022). "After examining secondary outcomes, we uncovered a significant association between mtDNA-CN and insulin sensitivity, likely driven by biological pathways that connect mitochondria, lipid accumulation, and insulin resistance." (PMID 35849594, 2022). "Obesity and insulin resistance are associated with increasing concentrations of circulating insulin that parallel elevated body weight and excess fat mass." (PMID 36117808, 2022). "Comparing with NCD group, HFD feeding caused obvious glucose intolerance and insulin resistance in mice after glucose and insulin load (i.p.), and resulted in higher values of area under the curve (AUC) for GTT and ITT, respectively." (PMID 36071929, 2022). "Aging is associated with several physiological changes that cause insulin resistance and impaired insulin secretion, which in turn lead to hyperglycemia." (PMID 36382752, 2022). "A higher intake of vegetable proteins from low-GI foods was associated with lower plasma insulin levels and insulin resistance." (PMID 35740583, 2022). "Insulin resistance and insulin signalling dysfunction in T2D are important risk factors for dementia and AD." (PMID 36003645, 2022). "Serum glucose and insulin concentrations and the insulin resistance index by the homeostatic model assessment for insulin resistance showed a positive association for weight gain." (PMID 35804768, 2022). "Conversely, iron overload decreases insulin sensitivity and induces insulin resistance, which is associated with reduced glucose uptake, and this occurs either by promoting ROS production or impairing autophagy." (PMID 35013137, 2022). "After Mirsky, the relative importance of defects in insulin release and insulin resistance were recognized as risk factors." (PMID 35163746, 2022). "Our findings suggest that RAGE-mediated adipose tissue insulin resistance is sex-specific, which is associated with different expression of genes involved in anti-oxidant and browning and insulin-induced AKT phosphorylation." (PMID 36348465, 2022).
Insulin resistance (continued). "In the future, the effect of standardized yoga therapy should be considered in the light of gene polymorphisms associated with insulin sensitivity and insulin resistance, which would open newer vistas in personalized medicine." (PMID 35089124, 2022). "DM is a result of the absolute or relative deficiency of insulin secretion and/or insulin resistance and is diagnosed as a high blood glucose level that can lead to a variety of secondary acute or chronic complications." (PMID 36005629, 2022). "The elevated levels of FBG and serum insulin are attributable to insulin resistance-caused hyperglycemia." (PMID 36290804, 2022). "Several studies have suggested that mitochondrial dysfunction is a major pathophysiological cause that impairs insulin secretion and induces insulin resistance in the development of type 2 diabetes." (PMID 35064188, 2022). "T2D concerns the majority of diabetic patients (around 90–95%) and is due to the development of insulin resistance that can result in a progressive loss of β-cell insulin secretion." (PMID 35185804, 2022). "When efforts began to establish the genetic aetiology of severe insulin resistance, the parsimonious assumption was that most causal genes would encode components of the insulin signalling pathway that was then being elucidated." (PMID 35618782, 2022). "It is thought that hyperglycemia, insulin resistance and subsequent increased activity of the insulin/IGF pathway drive the risk of endometrial cancer in this population." (PMID 36052252, 2022). "At the molecular level, two underlying mechanisms of insulin resistance have been proposed, both involving defective insulin signal transduction." (PMID 35883605, 2022). "Cardiac insulin resistance is linked to decreased cardiac insulin metabolic signaling and is caused by a variety of factors including oxidative stress, hyperglycemia, hyperlipidemia, and dysregulated adipokine/cytokine secretion." (PMID 36120460, 2022). "This contributes to the combined insulin resistance and impaired insulin secretion associated with poorly-controlled T2D and hyperglycemia." (PMID 35145074, 2022). "A genetic variant (rs2209972:C) associated with increased body mass index, higher fasting insulin levels, and insulin resistance in women with polycystic ovary syndrome in a Chinese population maps to the lncRAP2 gene body." (PMID 35036870, 2022). "The likely event causing hyperglycaemia in T2DM is dysfunction or loss of β-cells leading to reduced secretion of insulin and development of insulin resistance." (PMID 35475576, 2022). "Adiponectin, therefore, promotes fat storage in AT and increases insulin sensitivity, with its decrease in obesity a causal factor in insulin resistance, lipotoxicity, and metabolic syndrome manifestations." (PMID 36726470, 2022). "In humans with insulin resistance, the effect of insulin on reducing muscle protein breakdown is blunted causing increased muscle wasting, as is confirmed in rodent models." (PMID 35931683, 2022). "A linear regression model showed that WC, insulin, and Homeostatic model (assessment of insulin resistance) had positive associations with dietary Σω-6/Σω-3 ratio." (PMID 36381926, 2022). "Obesity is related to type 2 diabetes by causing insulin resistance, increasing fasting plasma insulin levels, and impairing glucose tolerance." (PMID 36014555, 2022). "A recent study showed that increased plasma levels of insulin and aldosterone in states of insulin resistance lead to reduced bioavailable nitric oxide, causing impaired vascular relaxation and pathological vascular stiffening." (PMID 35455055, 2022). "Insulin resistance is associated with elevated insulin levels, which stimulate hepatic triglyceride production in the setting of increased lipolysis and/or fat intake." (PMID 35624786, 2022).